VIM (vimentin)
Diseases named in the same sentence as VIM in open-access papers (continued):
Sharing a sentence is not in itself a finding about the gene and the disease.
breast carcinoma (continued). "In addition, BRD7 increased the expression of epithelial molecules such as E-cadherin and Claudin1 and decreased the expression of mesenchymal molecules such as Snail and vimentin in breast cancer cells." (PMID 32028981, 2020). "In our research, we also identified that the overexpression of circRNA_103809 could lead to the expression of epithelial mark (E-cadherin) increased, while the expression of mesenchymal markers (N-cadherin and vimentin) decreased in breast cancer cell lines." (PMID 32499818, 2020). "Similarly, Agelaki and colleagues found that EMT markers (Twist and Vimentin) are expressed in CTCs of patients with metastatic disease and in early breast cancer patients." (PMID 32391382, 2020). "In a dynamic in vivo model of metastatic breast cancer, Gilles and colleagues found that tumor cells in vascular tumoral emboli all express Vimentin (a marker of mesenchymal cells), but macrometastases in the lung display heterogenous Vimentin expression, and thus resemble the primary tumor." (PMID 32391382, 2020). "As a therapeutic approach inthis field, microRNA targeting against VIM was shownto decrease breast cancer invasion in animal studies.RhoA is another small GTPase with several functions,and it is known to be a key effector in the polymerizationof actin filaments." (PMID 31606974, 2020). "In this study, we found that co-culture of CD133+ HPCs, but not CD133- HUCBCs significantly decreased E-cadherin, but increased N-cadherin and Vimentin expression in breast cancer cells, indicating that CD133+ HPCs promoted the EMT process in breast cancer cells." (PMID 33243165, 2020). "In addition, Plk1 regulates cell surface levels of β1‐integrin and invasion by phosphorylating vimentin in breast cancer cells." (PMID 31040125, 2019). "In light of the information that Wi-A caused vimentin aggregation resulting in abrogation of invasion and metastases of the breast cancer cells, we examined the interactions of these two molecules with vimentin by bioinformatics and molecular docking (MD) tools." (PMID 31757995, 2019). "Indeed, vimentin is the most commonly used marker for the determination of a phenotype change from epithelial to mesenchymal for various models, including breast cancers." (PMID 30901969, 2019). "In breast cancer (in vivo and in vitro), epithelial markers such as E-cadherin and claudin were upregulated in response to luteolin while mesenchymal markers N-cadherin, vimentin, Snail and Slug were downregulated at dose-dependent manner." (PMID 31417401, 2019). "Vimentin, an intermediate filament protein, is highly expressed in aggressive epithelial cancers, including breast cancer, prostate cancer, gastric cancer, malignant melanoma, and lung cancer, where its expression level is associated with increased risks of metastasis." (PMID 31862882, 2019). "Up‐regulation of vimentin expression promotes breast cancer cell growth and metastasis." (PMID 31273950, 2019). "For paclitaxel resistance, the following miRNAs are relevant, miR-17-5P for the target PTEN in ovarian cancer, miR-30c for the targets VIM, IL-11 in breast cancer, miR-125b for Sema4C and Bak1 in breast cancer, and miR-100 for mTOR, miR-145 for P-gp in ovarian cancer, and miR-181a for PTEN in NSCLC." (PMID 35582143, 2019). "Indeed, a significant inverse relationship between RNF208 and Vimentin expression was observed in matched tumor tissues of patients with breast cancer." (PMID 31862882, 2019). "The previous study indicated that a non-invasive breast cancer cell line acquired increased motility and invasiveness upon Vimentin overexpression while the characteristics were down-regulated by silencing of Vimentin in an invasive tumor cell line that constitutively expressed." (PMID 31761784, 2019). "Since vimentin is biomarker of epithelial–mesenchymal transitions, which play a crucial role in cancer metastasis, we attempted to investigate the role of Rab7a in breast cancer cell migration." (PMID 29769411, 2019).
breast carcinoma (continued). "Furthermore, injection of MVT-1 mammary tumor cells with vimentin shRNA into a pre-diabetic mouse model showed the requirement of vimentin for metastasis in a pre-diabetic condition." (PMID 31126068, 2019). "Vimentin also showed an increase in the invasive forms of ductal (P-value=0.0238, 95% CI -0.0816653 to -0.0057547) and lobular (P-value=0.1457, 95% CI -0.0060373 to 0.0406173) breast carcinomas." (PMID 29907642, 2018). "D: Western blot showed the level of knockdown of vimentin in breast cancer cells." (PMID 30005669, 2018). "Furthermore, breast cancer cells with high endogenous vimentin expression were incapable for mesenchymal invasion inside three dimensional collagen I matrix after liprin-α1 knockdown due to disorganized vimentin network." (PMID 30005669, 2018). "However, treatment with JNKi caused a significant reduction in both mammary tumor growth and pulmonary metastasis in MDA231‐LM2 and SUM159‐LM1 xenograft models, as assessed by tumor volume and number of human vimentin‐positive foci in lung sections." (PMID 30190333, 2018). "To explore the molecular mechanism by which p62 promotes breast cancer invasion, we performed a co-immunoprecipitation–mass spectrometry analysis and revealed that p62 interacted with vimentin, which mediated the function of p62 in promoting breast cancer invasion." (PMID 28968743, 2017). "For example, miR-138 modulates metastasis and EMT in breast cancer cells by targeting vimentin, miR-122 regulates hypoxia-inducible factor-1 and vimentin in hepatocytes, miR-141 downregulates the expression of vimentin in renal tubular epithelial cells, and miR-200c suppresses vimentin." (PMID 27448976, 2017). "Thus, we examined the effect of FRK on the expression of well-known epithelial marker E-cadherin, and mesenchymal markers such as vimentin, fibronectin, slug and N-cadherin in breast cancer cells." (PMID 29348886, 2017). "Vimentin regulates lung cancer cell adhesion through focal adhesions and activates Slug, a transcription factor involved in epithelial mesenchymal transition in breast carcinoma." (PMID 29152145, 2017). "Vimentin expression has been shown to be elevated in several aggressive breast cancer cell lines and this increased expression positively correlates with increased migration and invasion of breast cancer cells." (PMID 28616237, 2017). "Together, these data suggest that p62 binds to vimentin in breast cancer cells." (PMID 28968743, 2017). "Finally, we assessed p62 and vimentin protein expression levels in clinical breast cancer specimens by western blot analysis." (PMID 28968743, 2017). "Furthermore, vimentin expression was found to correlate well with the poorly-differentiated and fibroblastic phenotype of breast cancer cell lines." (PMID 28225793, 2017). "In addition, the number of EMT CTCs detected by vimentin and twist increases during the progression of breast cancer through the early and late metastatic stages." (PMID 29271928, 2017). "For instance, keratin 14 is essential for the metastasizing invasive front of breast cancer, keratin 17 is an important transforming protein in Ewing Sarcoma, and vimentin is a marker of the epithelial to mesenchymal transition and induces the characteristic cellular changes of this transition." (PMID 29152145, 2017). "Moreover, metformin impeded the TGF-β-promoted loss of the epithelial marker E-cadherin in MCF-7 breast cancer cells and prevented TGF-induced cell scattering and accumulation of the mesenchymal marker vimentin in Madin-Darby canine kidney cells." (PMID 28147330, 2017). "Most importantly, vimentin is required for p62-promoted breast cancer metastasis." (PMID 28968743, 2017). "The extent and nature of vimentin expression in breast cancer has previously been reviewed." (PMID 27189371, 2016).
breast carcinoma (continued). "In the present study, we evaluated ER expression and the expression of the EMT-related markers E-cadherin and Vimentin in several cancer cell lines and tissues, confirming that T47D cells were epithelial luminal breast cancer cells and MDA-MB-231 cells were mesenchymal-like TNBC cells." (PMID 27124117, 2016). "Oestrogen receptor silencing of the ERα+ non-invasive MCF7 breast cancer cell line via siRNA resulted in oestrogen/tamoxifen-resistant cells that had altered morphology, increased motility, a switch from a CK to a vimentin-based cytoskeleton and increased invasive properties." (PMID 27189371, 2016). "In addition to elevation of E-cadherin, downregulations of ZEB1, N-cadherin, and vimentin were found in AESN-treated MCF-7 breast cancer cells." (PMID 27136519, 2016). "A finding based on breast cancer revealed that vimentin expression was noticed in 18% of cases and its expression correlated with high tumour grade and high growth fraction and study results revealed the association between vimentin expression and metastatic progression." (PMID 27190522, 2016). "However, study based on breast cancer showed that vimentin-positive cancers were more frequently found in younger women and other earlier findings confirmed correlation between basal markers expression and younger patient age." (PMID 27190522, 2016). "Indeed, CHEK2 down-regulation in fibroblasts paracrinaly induced the three major mesenchymal markers N-cadherin, Twist-1 and vimentin, and decreased two major epithelial markers E-cadherin and Epcam in breast cancer cells." (PMID 27484185, 2016). "MDA-MB231, together with the non-tumorigenic cell line MCF-10A, is the only breast cancer cell line to express the mesenchymal marker vimentin, while all the other three breast cancer cell lines (MCF-7, SKBR3 and MDA-MB468) express the epithelial marker E-cadherin." (PMID 26735339, 2016). "Despite questioning the degree to which EMT is responsible for the vimentin expression observed in invasive breast cancers, they concluded that vimentin expression was evidence of the final step of de-differentiation in tumours and was associated with invasion." (PMID 27189371, 2016). "Two of the 3 LAR models were KRT5 and KRT17 negative at the protein level, Vimentin was highly expressed in 2 out of 3 metaplastic breast cancer, which also showed loss of E-cadherin expression." (PMID 27374081, 2016). "Similarly, Slug induces vimentin and Axl to contribute to the migration and lung metastasis of breast cancer cells." (PMID 27385093, 2016). "In addition, we also verified that GSN plays a role in the gene expression for the mesenchymal cell marker, vimentin in breast cancer cells with GSN op and/or siGSN approaches." (PMID 26482896, 2015). "Indeed, miR-200c upregulation after treatment with one of these compounds inhibited ZEB1 expression, resulting in E-cadherin induction and vimentin inhibition in breast cancer cell lines." (PMID 26423775, 2015). "Therefore, the high level of vimentin observed in this study was positively correlated to the poor prognosis of breast cancer patients who had received cocktail chemotherapy." (PMID 25965826, 2015). "The same samples were also immunostained for vimentin, a breast cancer aggressiveness marker." (PMID 25868856, 2015). "In line with our findings in HeLa cells, reactivation of KLK6 in breast cancer cells was associated with prominent down-regulation of Vimentin in the absence of a parallel rise in E-cadherin (unpublished data)." (PMID 25990935, 2015). "Furthermore, the overexpression of vimentin in breast cancer cells is correlated with poor prognosis, leading to adverse clinicopathological features in patients." (PMID 26702618, 2015). "The aim of the present study was to assess whether vimentin and Notch gene and protein expression are altered in breast cancer progression." (PMID 24527079, 2014). "Vimentin is known to be selectively expressed in aggressive breast cancer cell lines." (PMID 24527079, 2014).
breast carcinoma (continued). "The importance of vimentin expression was analyzed by identifying cases of breast cancer with poor prognosis and comparing vimentin and Notch as biomarkers required for prognosis in breast cancer patients." (PMID 24527079, 2014). "Furthermore, it has been shown that overexpression of vimentin in the non-invasive MCF7 breast cancer cell line increases invasiveness." (PMID 25171249, 2014). "Accordingly, expression of Vimentin can be found in many aggressive breast cancer cell lines." (PMID 25050175, 2014). "Overexpression of vimentin IFs in the breast carcinoma model leads to augmentation of motility and invasiveness in vitro, which can be transiently downregulated by treatment with antisense oligonucleotides to vimentin." (PMID 25140302, 2014). "This suggests that vimentin may play a pivotal role in fluvastatin mediated cytotoxicity in MDA-MB-231 breast cancer cells." (PMID 25268751, 2014). "Vimentin, an epithelial- mesenchymal transition marker, is elevated in various epithelial cancers including breast cancer and recently it was also highlighted as a potential therapeutic target for cancer because of its role in proliferation, migration and invasion." (PMID 25268751, 2014). "However, vimentin is frequently expressed in neoplastic cells with metastatic properties, including breast cancer cells." (PMID 24527079, 2014). "The histological and immunohistochemical comparison of the xenograft and the human sample were close to identical with the exception of reduced human vimentin staining, reflecting mouse stroma, as previously demonstrated also in primary breast cancer xenografts." (PMID 24594904, 2014). "A species-specific distribution of these progenitors might explain why in cats mammary cancer is frequently an aggressive, triple-negative, vimentin-positive carcinoma." (PMID 25249140, 2014). "The screens were done in metastatic breast cancer cells expressing vimentin at high levels and three novel vimentin regulators - WAS/WASL interacting protein family member 2 (WIPF2), methylenetetrahydrofolate dehydrogenase 2 (MTHFD2) and ephrin type-B receptor 4 (EPHB4) were identified." (PMID 23295955, 2013). "Previous reports have shown the role of vimentin in breast cancer progression." (PMID 23341946, 2013). "Moreover, HDGF protein also regulates the EMT in breast cancer cells through modulation of E-cadherin and vimentin expression." (PMID 23536873, 2013). "Vimentin is a regulator of cell migration and invasion in breast cancer cells." (PMID 23295955, 2013). "Especially, epithelial cells coexpressing cytokeratins 5/19 and vimentin have been identified by dual immunofluorescence labeling in claudin-low and basal-like breast cancers, two breast cancer subtypes frequently exhibiting overexpression of EMT-inducing transcription factors." (PMID 22654675, 2012). "For this, we used 4T1 mouse breast carcinoma cells that possess an intermediate phenotype, growing as clusters of loosely attached cells in 2D and expressing E-cadherin as well as some mesenchymal markers such as vimentin." (PMID 22347456, 2012). "Furthermore, in breast cancer it has been shown that cells with a high expression of vimentin are highly sensitive to dasatinib." (PMID 23049743, 2012). "The expression of vimentin may be mediated by β-catenin in TERT-siSFRP1 cells since β-catenin can transactivate vimentin in breast cancer cells and β-catenin activity is enhanced in TERT-siFRP1 cells." (PMID 21303533, 2011). "Furthermore, our experiments revealed that CK+Twist+ and CK+vimentin+ CTCs were also observed in patients with early stage breast cancer." (PMID 21663619, 2011). "Vimentin overexpression was found in 90.5% of grade III breast carcinomas which may explain its presence in both HER2-positive breast cancer and in TNBC." (PMID 22110952, 2011).
breast carcinoma (continued). "Moreover, a significant association was also observed between vimentin-positive and α-SMA-positive fibroblasts or CAF in tumour microenvironment in 37 of 39 (95%) cases of primary breast cancer and in 36 of 39 (92%) cases of lymph node metastases." (PMID 21897388, 2011). "Recently Lester and colleagues reported that when MB468 breast cancer cells were cultured in a hypoxia condition expression of uPAR was increased, cell-cell junctions were disrupted, vimentin expression was increased, and E-cadherin was lost from cell surfaces, indicating enhancement of EMT." (PMID 20540763, 2010). "Expression of vimentin and cytokeratins has also been described in breast carcinomas." (PMID 19695088, 2009). "The basal cytokeratin-negative tumors that clustered with the basal-like cluster in this study could be EGFR, vimentin, and/or c-kit-expressing tumors with a similar gene expression signature to that of basal cytokeratin-immunopositive breast cancers." (PMID 17263897, 2007). "Vimentin was selectively overexpressed in highly aggressive breast cancer cells." (PMID 17325702, 2007). "As mutations in vimentin have been reported in patients around the area of C328, our hypothesis that this mutation induces conformational changes that activate the complex processes of EMT in breast cancer cells would have clinical implications." (PMID 40690373, 2025). "Finally, we tested whether CXCL8 and CXCL1 expressions correlate with EMT-associated genes, including VIM (gene for Vim), SNAI1 (gene for Snail1), and TWIST1 (gene for Twist1) in breast cancer cell lines using the HMS LINCS dataset." (PMID 40833805, 2025). "Recent scholarly contributions have posited that VIM's degradation could curtail the proliferation and metastasis of breast cancer cells, thereby underscoring its potential utility as both a biomarker and therapeutic target within the domain of breast oncology." (PMID 39781570, 2025). "Clinical samples obtained from breast cancer patients who exhibited poor outcomes, including advanced stages, lymph node metastases, and decreased disease-free survival rates, underscore a direct relationship between increased vimentin and Slug expression and decreased miR-30a levels." (PMID 38339408, 2024). "Combined with basal breast cancer markers CK 6 and Vimentin, the MAPK-signaling protein Erk1/2- pThr202/Tyr204 and the active mTOR signaling protein eIF4E-pSer209, these proteins could differentiate PAB resistant from PAB sensitive BC-PDMs (Mann Whitney U-test, ***p < 0.001)." (PMID 37596623, 2023). "Importantly, the expression of Vimentin strongly correlated with invasion-related markers CXCR4 and uPAR, and stemness markers Nanog, Oct4 and ALDH1, indicating the close association with a higher risk of death in early breast cancer." (PMID 36768876, 2023). "Organophosphorus pesticide exposure enhanced the protein expression of EMT associated proteins vimentin, ax1, and slug, while chlorpyrifos (CPF), one of the most frequently used pesticides around the world, increased MMP2 and vimentin expression driving breast cancer invasion." (PMID 37511154, 2023). "Furthermore, present data suggest that SMRwt peptide could block breast cancer metastasis through mechanisms involving target protein Mortalin and Vimentin that decrease proliferation, tumorigenesis, and tumor exosome release." (PMID 35915218, 2022). "In addition, Vimentin is overexpressed in various epithelial cancers, including prostate cancer, gastrointestinal tumors, tumors of the central nervous system, breast cancer, malignant melanoma, and lung cancer, indicating that ERBB2 promotes ESCC cell migration." (PMID 35524932, 2022).